IL33 (interleukin 33)
Diseases named in the same sentence as IL33 in open-access papers (continued):
Sharing a sentence is not in itself a finding about the gene and the disease.
autoimmune disease (continued). "IL-33 is a member of the IL-1 family and plays an ambivalent role in autoimmune diseases." (PMID 39846845, 2025). "We specifically explored whether genetic variations in IL-33 contribute to this condition, as has been observed in other autoimmune disorders." (PMID 39769469, 2024). "Additionally, an in vitro and in silico analysis revealed that compounds 10 and 11 exhibited significant potential as suppressor compounds in autoimmune diseases (ADs) by modulating the IL-33/ST2 signaling pathway." (PMID 39061836, 2024). "Furthermore, we assessed the inhibitory effects of these substances on IL-33/ST2 signaling in processes related to inflammatory and autoimmune diseases using an enzyme-linked immunosorbent assay." (PMID 39061836, 2024). "In recent years, IL-33 was shown to potentiate the proliferation and function of tissue-derived Tregs and is currently considered a potential therapy to increase Treg activity in autoimmune diseases." (PMID 39704171, 2024). "IL-33 also began to be studied in the cardiovascular system and in autoimmune diseases." (PMID 37153553, 2023). "IL-33 activation mediates inflammation in autoimmune diseases." (PMID 36362030, 2022). "Therefore, periodontitis and autoimmune diseases share many pathological aspects, including IL-1 and IL-33 production." (PMID 36362030, 2022). "IL-33 is involved in the polarization of T cells towards the Th2 cell phenotype and MC activation and plays a crucial role in inflammatory, infectious, and autoimmune diseases." (PMID 32560266, 2020). "Furthermore, IL-33 is an inducer of Th2 immune responses and presents a pivotal role in the development of many autoimmune diseases, such as SLE." (PMID 33102506, 2020). "Moreover, the role of IL-33/ST2 in a vast array of autoimmune diseases emerged, because of the detection, in patients' serum, of elevated ST2 levels." (PMID 29713240, 2018). "There are several studies reported that IL-33 suppressed Th17 response in autoimmune disease." (PMID 30539029, 2018). "Other studies suggest that increased IL-33 levels correlate with the acute-phase inflammatory response in autoimmune diseases such as systemic lupus erythematosus where the levels of serum IL-33 are positively correlated with the erythrocyte sedimentation rate (ESR) and C reactive protein (CRP)." (PMID 30034292, 2018). "The IL-33/ST2 axis is involved in the pathogenesis of autoimmune diseases." (PMID 28415811, 2017). "Treg cell expansion by IVIG in patients with autoimmune diseases lack correlation with IL-33." (PMID 28320438, 2017). "For the autoimmune diseases above, either IL-33 or ST2 expression was altered in the serum of active patients, and this may be correlated with inflammatory cytokines, such as TNF-alpha and IL-1beta." (PMID 24151520, 2013). "Furthermore, IL-33 which is the new member of IL-1 may relate to autoimmune diseases and periodontitis because of its ability to activate the secretion of proinflammatory cytokines via nuclear factor kappa-B." (PMID 37940896, 2023). "Hence, modulation of IL-33 produced by MCs may represent a promising strategy for the treatment of autoimmune diseases where cytokine dysregulation occurs." (PMID 32560266, 2020). "In addition, IL-33 has a potential role in autoimmune disease development." (PMID 32064263, 2019). "In support of this hypothesis, inhibition of the IL-33/ST2 pathway via neutralizing ST2 antibodies or using ST2 KO mice in models of autoimmune disease (e.g., dextran-induced colitis, collagen-induced or autoantibody-induced arthritis) demonstrated reduced severity of disease pathology." (PMID 30574145, 2018). "Therefore, studies on IL-33 may provide a new idea and target for the treatment of autoimmune diseases." (PMID 25032216, 2014).
autoimmune disease (continued). "IL-33 upregulation is likely to cause an overactive immune response even when no infection is present, hence may be driving autoimmune disease, making it essential to understand its pathway (activation/inhibition) for potential therapeutic intervention in localized scleroderma." (PMID 39408800, 2024). "Several previous studies have suggested that IL-33 contributes to the pathogenesis of autoimmune diseases, especially in patients with SLE and lupus nephritis; the expression of IL-33 and its receptor ST2 is significantly upregulated." (PMID 36421424, 2022). "IL-33/ST2 signaling has been found to upregulate CD11b, TLR4, caspase-1, and IL-1β in a number of human and animal studies of infection and autoimmune disease." (PMID 36741845, 2022). "It must be stressed that the involvement of the IL-33/ST2 axis in the pathogenesis of SLE is very difficult to distinguish from its role, and from the facts shown in other autoimmune diseases." (PMID 35328556, 2022). "Increasing evidence supports the conclusion that IL-33/ST2 signaling is involved in the pathophysiology of SLE and other autoimmune diseases." (PMID 33182616, 2020). "There is growing evidence suggesting that IL-33/ST2 axis plays an important role in chronic in?ammatory and autoimmune diseases; type 2 diabetes, in?ammatory bowel disease, cardiac disease, graft-vs.-host disease and small bowel transplant rejection." (PMID 30498495, 2018). "Our findings indicate that IL-10 act as a negative regulator of IL-33/ST2 signaling pathways in vivo, suggesting a potential therapeutic role of IL-10 in autoimmune diseases." (PMID 28415811, 2017). "And further study of IL-33 and ST2 structure, function, and signal transduction pathways involved in autoimmune diseases is required." (PMID 25032216, 2014). "This review focuses on new findings in the roles of IL-33 and ST2 in several kinds of T cell-mediated autoimmune diseases." (PMID 25032216, 2014). "The administration of interleukin 33 and deletion of IL-33 receptor, ST2 molecule, affects the induction of autoimmunity in different experimental models of human autoimmune diseases." (PMID 23028861, 2012). "Therefore, IL-33 together with ST2 play an important role as a cytokine in the progression of inflammation and autoimmune diseases." (PMID 39925809, 2025). "The IL-33/ST2 axis was initially evaluated in relation to the ability to influence neoplastic growth, and later in relation to cardiovascular diseases, inflammatory conditions, fibroproliferative diseases, autoimmune diseases, and systemic infections." (PMID 35897800, 2022). "Thus, the IL-33/ST2 axis plays an essential role in inflammatory and autoimmune diseases, both in animal models and in clinic practice." (PMID 36291105, 2022). "In addition, IL-33 induces vascular endothelial growth factor (VEGF) secretion from human MCs and is increased in autoimmune disorders, including psoriasis, contributing to the inflammatory state." (PMID 32560266, 2020). "Comprehensive reviews of the biology of IL-33 and its involvement in non-allergic conditions including autoimmune diseases and cancer have recently be described elsewhere." (PMID 30233590, 2018). "However, IL-33−/− mice fail to develop autoimmune disease, and no one has shown whether nuclear IL-33 has been found in immune cells." (PMID 28484466, 2017).
helminth infection (76 papers, 2012 to 2026). "In A. suum, the helminth-infection hallmark cytokines IL-13, IL-25 and IL-33 were identified as potential targets of lin-4-5p and let-7-5p, miR-5350d-5p and miR-87a/b-3p, respectively." (PMID 38172997, 2024). "Both IL-13 and IL-33 have been implicated in type 2 imprinting of macrophages or ILC2 during helminth infection, respectively." (PMID 36065058, 2022). "In the small intestine, IL-33 promotes the generation of iILC2s by induction of tryptophan hydroxylase 1, deletion of which results in increased susceptibility to helminth infection." (PMID 35707544, 2022). "Eosinophils, largely associated with the response to helminth infection and allergies, have also been proven to possess strong anti-helminthic effects mediated by IL-33." (PMID 32363166, 2020). "IL-33, a cytokine released during helminth infection, causes the activation and proliferation of MC through interaction with the ST2 receptor." (PMID 30670631, 2019). "Similarly, in many helminth infections IL-33 administration can drive immunity, while deficiency of IL-33 or the IL-33 receptor leads to increased parasite load." (PMID 29045903, 2017). "Thus, IL-33 signalling is restricted to type 2 immune cells – cells majorly associated with allergy and helminth infection." (PMID 23521712, 2013). "Thus, we believe that the IL-33/ST2 pathway influences the formation of granulomas during helminth infections and may be associated with eosinophils." (PMID 34324507, 2021). "Mast cells express the highest levels of the IL-33 receptor subunit ST2 of any immune cell, and mast cells can mediate type 2 immune inflammation; however, the role of IL-33-driven mast cell responses in helminth infection is poorly understood." (PMID 41906940, 2026). "The IL-33/ST2 pathway is important as part of the type 2 immune response against helminth infections." (PMID 41906940, 2026). "IL‐33 signalling contributes to protection against helminth infections in mice such as Heligmosomoides polygylus, L. sigmodontis, Nippostrongylus brasiliensis, Strongyloides ratti and Trichinella spiralis." (PMID 39654685, 2024). "In the same helminth infection model, IL-33 released by myeloid cells induced regulatory T cell expansion, suppressing effector immune responses and resulting in increased parasite burdens." (PMID 39514278, 2024). "Following helminth infection of the small intestine, stromal cells in adjacent adipose tissue start producing interleukin-33 (IL-33) and thymic stromal lymphopoietin (TSLP)." (PMID 39107476, 2024). "Previous work showed that IL-33, a cytokine upregulated in inflammatory bowel disease and helminth infections like N. brasiliensis, induces intestinal goblet cells and Muc2 expression in mice through IL-13 production by innate lymphoid cells." (PMID 38721267, 2024). "At the later stages of helminth infection, iILC2s can become responsive to IL-33 and give rise to nILC2s." (PMID 36969171, 2023). "Taken together, our results reveal an IL-17A-neutrophil-axis that can drive IL-33 during helminth infection, highlighting an additional pathway by which IL-17A regulates pulmonary type 2 immunity." (PMID 37783278, 2023). "In 2019, Madelene W Dahlgren identified a new feedback function for IL-33 following helminth infection." (PMID 37153553, 2023). "The early migratory phase of pulmonary helminth infections is characterized by tissue injury leading to the release of the alarmin interleukin (IL)-33 and subsequent induction of type 2 immune responses." (PMID 37783278, 2023). "In contrast, the downregulation of IL1B observed on day 3 probably results in IL-25 and IL-33 suppression, supporting chronic helminthic infection." (PMID 37600806, 2023). "Of note, ChAT+ ILC2s are strongly induced by type 2 inflammatory conditions, such as helminth infection, Alternaria sensitization, and IL-25 and IL-33 treatment." (PMID 35707544, 2022).
helminth infection (continued). "iILC2 cells express more IL-25R and develop into nILC2-like cells, producing IL-5 and IL-13 after stimulation with IL-33 during worm infection." (PMID 35707544, 2022). "Induction of Tph1 in helminth infection is dependent on IL-33 and is important for the generation of iILC2s and the immune response against the parasites." (PMID 34759931, 2021). "The important role of IL-33 in allergic reactions, helminth infection, cancer, tissue fibrosis, chronic inflammation, organ transplantation, and rheumatic immune diseases has been extensively studied in recent years." (PMID 34589505, 2021). "The type 2 cytokines IL-5 and IL-13 are also secreted early during a helminth infection by innate lymphocytes (ILC2) in response to the release of IL-33 and TSLP from mucosal epithelial sensor cells." (PMID 34083746, 2021). "Helminth infections usually trigger a Th2 immune response in the host, by releasing cytokines such as IL-4, IL-5, IL-13 and IL-33." (PMID 34324507, 2021). "For example, IL-33 is produced by adventitial stromal cells during helminth infection whereas type II pneumocytes and white adipose tissue-resident stromal stem cells produce IL-33 in other settings of type-2 inflammation." (PMID 32793230, 2020). "Despite mounting evidence of the importance IL-33 plays in clearance of helminth infection, there remains a great deal to be uncovered, as this species specificity necessitates work across the broad body of organisms that exist." (PMID 32363166, 2020). "Taken together, these results paint a clear picture of the critical role the innate immune system plays in response to helminth infection that is, at least in part, mediated through IL-33 released at first contact by invading parasites." (PMID 32363166, 2020). "As an alarmin, IL-33 proceeds to function to promote an early shift toward a type 2 immune response, protective in the context of helminth infection." (PMID 32363166, 2020). "In this review article we compile the current cutting-edge research into the interleukin-33 response to toxoplasmosis, malaria, leishmania, and helminthic infection." (PMID 32363166, 2020). "A more systemic analysis performed on naïve ILC2 or ILC2 isolated from IL-33 injected or helminth infected mice identified multiple immunoregulatory miRNAs that were upregulated following IL-33 administration or helminth infection, including miR-155." (PMID 31574995, 2019). "The activity of IL-33 has centered around its contribution to protective “weep and sweep” defenses during helminth infection, however, this work expands IL-33’s relevance to gut bacterial immunity." (PMID 31221971, 2019). "IL-33 is a cytokine that targets immune response to Th2 following helminth infection, and its profibrogenic effect on bleomycin fibrosis induction has been demonstrated, mainly due to its role in M2 macrophage polarization, and expressing arginase." (PMID 31765381, 2019). "The canonical role of IL-33 is in the elicitation of type 2 immunity and it is integral to the innate response to certain helminth infections." (PMID 31231388, 2019). "In response to helminth infection, innate immune cells and intestinal epithelial cells secrete Th2 cytokines including IL-4, IL-5, IL-9, IL-13, IL-25, IL-33 and thymic stromal lymphopoietin (TSLP)." (PMID 30670631, 2019). "IL-33 plays a critical role in host defense to helminth infections via the cytokine-driven activation of ILC2, increased IgA levels and elevated goblet cell hyperplasia." (PMID 31574995, 2019). "Additional miRNAs were also regulated uniquely in response to IL-33 administration or worm infection, respectively." (PMID 30356668, 2018). "These authors revealed a novel mechanism of suppressing Th2 response onset via inhibition of IL-33 released from necrotic epithelial cells which are insulted during helminth infection and exposure to airway allergens." (PMID 30369927, 2018).
helminth infection (continued). "Recently, numerous studies have highlighted that tissue damage, which induces the release of cytokine alarmins such as IL-33, is a potent mechanism driving type 2 immunity, particularly in the context of helminth infection." (PMID 29554131, 2018). "To examine the role of IL-33 in the enhanced lung inflammation induced by subsequent helminth infection, we infected Sv-exp WT and Il33−/− mice with N. brasiliensis." (PMID 30283458, 2018). "In helminth infections, type 2 immunity is initiated at the site of invasion by epithelial cells, which release the alarmins IL-25 and IL-33, inducing innate lymphoid cells (ILCs) to produce IL-13 and other cytokines." (PMID 28302598, 2017). "They expand strongly in vivo in response to IL-25 and IL-33, and represent the predominant early source of IL-5 and IL-13 during allergic inflammation and worm infection." (PMID 25659095, 2015). "Current knowledge surrounding the impact of ST2/IL-33 interactions on helminth infections is based on studies using intestinal helminths." (PMID 24663956, 2014). "During helminth infection, intestinal epithelial cells induce the production of IL-25, IL-33, and TSLP." (PMID 23653627, 2013). "IL-33, a proposed alarmin, stimulates innate immune cells and Th2 cells to produce IL-13 and is rapidly upregulated upon antigen exposure in murine helminth infection." (PMID 23521712, 2013). "IECs are thought to represent the major source of early IL-25 and IL-33 following helminth infection." (PMID 23935505, 2013). "Responses to the alarmin cytokine IL-33 are also strongly implicated in immunity to helminths, with increased susceptibility of mice deficient in either IL-33 or the IL-33 receptor (ST2) seen in a wide range of helminth infections." (PMID 40302223, 2025). "The first evidence for the role of IL-33 in host defense was in helminth infection." (PMID 39962262, 2025). "Likewise, IL-33 responses are important for induction of anti-parasite type 2 immune responses in helminth infections." (PMID 39514278, 2024). "Natural ILC2s (nILC2) are IL-33 responsive and can be found in the lungs in homeostatic conditions, whereas inflammatory ILC2s (iILC2) respond to IL-25 and emerge after IL-25 treatment or during helminth infection." (PMID 36969171, 2023). "As IL-33 is central to helminth infection control, it would be extremely interesting to determine if IL-33 is participating in the training of ILC2s and macrophages for the control of helminth infection." (PMID 37325618, 2023). "During helminth infections, neutrophils may exhibit the expression of IL-13 and IL-33 and fall into the category of N2 neutrophils, although further in vivo experiments are necessary to validate this occurrence." (PMID 38203591, 2023). "The alarmins IL-33, IL-25 and TSLP are mainly secreted by stromal and epithelial cells in tissues and were linked to chronic inflammatory diseases, such as allergic lung inflammation, or to resistance against worm infections." (PMID 37063913, 2023). "IL-33 mediates the activation of ILC2s and Treg cells in tissues after worm infection, and the Treg cell accumulation in vivo required ILC2s activation, which was independent of ILC2s secreted cytokines but partially dependent on direct co-stimulatory interactions via ICOSL:ICOS." (PMID 35592688, 2022). "Furthermore, the increased levels of these type II cytokines induced by worm infection were also reversed in IL-33 KO mice." (PMID 36271450, 2022). "During helminth infection, adventitial stromal cell depletion impairs the accumulation and function of lung ILC2s and Th2 cells partially dependent on adventitial stromal cells-derived IL-33, thus impairing the effect of expelling helminth." (PMID 35592688, 2022). "However, it has also been reported that IL-33 stimulation can promote nILC2s to become iILC2s, thus generating a population that is important for the correct immune response against helminth infection." (PMID 34759931, 2021).